MMP11 (matrix metallopeptidase 11)
Diseases named in the same sentence as MMP11 in open-access papers (continued):
Sharing a sentence is not in itself a finding about the gene and the disease.
benign breast tumors (1 paper, 2023). "Luminal A-like BC subtypes had higher MMP-11 expression than benign breast tumors and other subtypes of BC." (PMID 37798646, 2023). "The mRNA expression of MMP-11 was 5.1 times higher in BC than in benign breast tumors cases and the difference was statistically significant (P = 0.012)." (PMID 37798646, 2023). "In the present study, the MMP-11 expression was shown to be significantly higher in BC cases compared to benign breast tumors." (PMID 37798646, 2023). "The MMP-11 expression was higher in BC than in benign breast tumors." (PMID 37798646, 2023). "In particular, MMP-11, but also MMP-2, and MMP-9 were higher in BC when compared with benign breast tumors." (PMID 37798646, 2023).
bladder tumor (1 paper, 2017). "In total, five articles investigating four different MMPs types (MMP1, MMP7, MMP9, and MMP11) reported a relationship between abnormal levels of MMPs and bladder tumor progression." (PMID 28427222, 2017).
bone cancer (1 paper, 2020). A primary or metastatic malignant neoplasm affecting the bone or articular cartilage. "Involved in bone cancer metastasis acting alongside MMP-1 and MMP-11." (PMID 32116759, 2020).
brain-tumors (1 paper, 2024). "Moreover, the Human Tumor Metastasis RT2 Profiler PCR Arrays showed that exposure to NA diminishes the presence of matrix metallopeptidase-11 (MMP-11), an enzyme related to the breakdown of the extracellular matrix whose expression is higher in GB than in non-malignant-brain-tumors." (PMID 39153092, 2024).
cholangiocarcinoma (1 paper, 2023). A carcinoma that arises from the intrahepatic biliary tree (intrahepatic cholangiocarcinoma) or from the junction, or adjacent to the junction, of the right and left hepatic ducts (hilar cholangiocarcinoma). "Another example of assessing MMP-11 expression is cholangiocarcinoma, which is a primary tumor of the bile duct mucosa." (PMID 38203373, 2023). "The authors concluded that positive expression of MMP-11 indicates a poor prognosis in samples with cholangiocarcinoma." (PMID 38203373, 2023).
chronic hepatitis C (1 paper, 2017). "Then, our work is the first study conducted on a large cohort of well-characterized patients with chronic hepatitis C. It demonstrates a marked down-regulation of miR-125a in tumor tissue and a subsequent up-regulation of its oncogenic targets MMP11, SIRT7 and c-Raf." (PMID 28445974, 2017).
Cirrhosis (1 paper, 2023). A chronic disorder of the liver in which liver tissue becomes scarred and is partially replaced by regenerative nodules and fibrotic tissue resulting in loss of liver function. "QuantSeq 3′ mRNA sequencing revealed thirty-three downregulated genes associated with ECM after the NK cell treatment of CCl4-induced cirrhosis, including six MMP genes (MMP3, MMP8, MMP9, MMP11, MMP12, and MMP14)." (PMID 37189708, 2023).
craniosynostosis (1 paper, 2023). Craniosynostosis is defined as the premature fusion of one or more cranial sutures leading to secondary distortion of skull shape resulting in skull deformities with a variable presentation. "MMP11 exhibited decreased expression in female coronal craniosynostosis compared to controls and was also decreased in the primary models for the coronal, metopic, and sagittal phenotypes, and male models for metopic and sagittal phenotypes." (PMID 36982425, 2023).
cryptorchidism (1 paper, 2012). The failure of one or both testes of a male fetus to descend from the abdomen into the scrotum during the late part of pregnancy. "Furthermore, study of hFFCs derived from HS and cryptorchidism (CO) patients (n = 23 and 11, respectively) indicated that MMP11 expression was significantly lower in the HS group than in the CO group (0.25-fold, P = 0.0027)." (PMID 22574217, 2012).
dysplasia (1 paper, 2026). A usually neoplastic transformation of the cell, associated with altered architectural tissue patterns. "Importantly, our results suggest that MMP11 expression may serve as a predictive factor for recurrence independent of dysplasia." (PMID 40843631, 2026).
Fibroadenoma (1 paper, 2020). A benign tumor of the breast characterized by the presence of stromal and epithelial elements. "For fibroadenoma tissues, compared with both fibroadenoma-adjacent and normal tissues, there were six up-regulated (ANXA6, VCP, SERPINH1, galactosidase alpha, NNT, and MMP11) and 38 down-regulated (KRT10, KRT1, ALDH1A1, ECM1, and others) proteins in fibroadenoma." (PMID 33194682, 2020).
glomerulonephritis (1 paper, 2023). A renal disorder characterized by damage in the glomeruli. "The highest incidence of MMP-11 was reported in glomerulonephritis." (PMID 38203373, 2023).
Hypertension (1 paper, 2017). The presence of chronic increased pressure in the systemic arterial system. "Apart from Mmp11 which is a matrix metalloproteinases as Mmp2 we selected Ptgs1, Ptgs2 and Olr1 due to their possible relation to the vascular changes associated with hypertension." (PMID 28880918, 2017).
inflammatory bowel disease (1 paper, 2023). A spectrum of small and large bowel inflammatory diseases of unknown etiology. "Literature data indicate that the main biomarkers of inflammatory bowel diseases are four MMPs, i.e., MMP-3, MMP-7, MMP-9, and MMP-11." (PMID 38203373, 2023).
intestinal tumour (1 paper, 2003). "A number of different MMPs may be important in intestinal tumour formation as human tumours have been shown to express interstitial collagenase (MMP-1), gelatinase A (MMP-2), stromelysin 1 (MMP-3), matrilysin (MMP-7), gelatinase B (MMP-9), and stromelysin 3 (MMP-11)." (PMID 12778076, 2003).
intraepithelial squamous lesions (1 paper, 2005). "Expression of MMP11 in intraepithelial squamous lesions suggest that, as in squamous lung carcinomas, it could be related to progression of phenotypic alterations acquired early during the malignant transformation pathway of cervical epithelium and it is maintained after invasion." (PMID 15989693, 2005).
invasive carcinoma (1 paper, 2005). A carcinoma that is not confined to the epithelium, and has spread to the surrounding stroma. "MMP11 expression was significantly higher in invasive carcinomas." (PMID 15989693, 2005).
ischemia (1 paper, 2022). A hypoperfusion of the BLOOD through an organ or tissue caused by a PATHOLOGIC CONSTRICTION or obstruction of its BLOOD VESSELS, or an absence of BLOOD CIRCULATION. "In contrast, transcriptomic levels of Mmp11, Mmp23, and Mmp28 exhibited a bimodal pattern: their mRNA expression was downregulated in the first 24 h after ischemia, whereas significant upregulation was observed in the infarcted tissue isolated from day seven to day 21 post-MI." (PMID 36555255, 2022).
lobular invasive carcinoma (1 paper, 2024). "In our study, we observed the absence of epithelial MMP-11 expression, which could be attributed to the specific composition of our cohort, notably the exclusion of lobular invasive carcinoma and rare subtypes." (PMID 38438841, 2024).
mesothelioma (1 paper, 2025). A usually malignant and aggressive neoplasm of the mesothelium which is often associated with exposure to asbestos. "Meanwhile, Kaplan-Meier curves showed that higher MMP11 expression was associated with shorter overall survival (OS) in diverse tumors including BLCA, GBMLGG, KICH, LGG, PAAD, SARC, UVW, and mesothelioma." (PMID 40607407, 2025).
Myocardial fibrosis (1 paper, 2019). "MMP11 belongs to the family of proteolytic enzymes that regulate extracellular matrix and play a role in the development of myocardial fibrosis and ventricular remodeling." (PMID 31554410, 2019).
myocardial infarction (1 paper, 2014). Gross necrosis of the myocardium, as a result of interruption of the blood supply to the area, as in coronary thrombosis. "Meanwhile, recent studies showed that a variety of MMPs increase in the myocardium after myocardial infarction, including MMP-1, MMP-2, MMP-3, MMP-7, MMP-9, MMP-11, and so on." (PMID 25237357, 2014).
myopia (1 paper, 2012). "Association tests for myopia using logistic regression indicated the best p-value (unadjusted) was 0.04 at rs28382576 for MMP11." (PMID 23077567, 2012). "Initial findings indicated that the best p values for each trait were 0.02 for myopia at rs2274755 (MMP9), 0.02 for SE at both rs3740938 (MMP8) and rs131451 (MMP11), 0.01 for axial length at rs11225395 (MMP8), 0.01 for anterior chamber depth at rs498186 (MMP1) and 0.02 at rs10488 (MMP1)." (PMID 23077567, 2012).
nasopharyngeal carcinoma (1 paper, 2015). A carcinoma arising from the nasopharyngeal epithelium. "In another study, knockdown of CD147 reduced the secretion of MMP-11 in nasopharyngeal carcinoma." (PMID 26507719, 2015).
oral cavity cancer (1 paper, 2024). A primary or metastatic malignant neoplasm involving the oral cavity. "Similar findings have also emerged for other cancer types, including MMP-11 expression in spindle-shaped tumor cells of oral cavity cancers, in prostate and pancreatic tumor cells." (PMID 38438841, 2024).
papillary thyroid carcinoma (1 paper, 2015). "In another study, there was an inverse relationship between MMP-11 expression and predictors of poor prognosis of papillary thyroid carcinoma." (PMID 26507719, 2015).
periodontal disease (1 paper, 2021). "All of these are constituent ECM proteins found to be upregulated by T. denticola challenge, highlighting MMP-11 as a potentially unique response regulator underpinning periodontal disease progression." (PMID 34255809, 2021). "Interestingly, Membrane-type matrix metalloproteinase 4 (MMP-17), Stromelysin-3 (MMP-11) and Epilysin (MMP-28) were consistently clustered with various GO terms associated with ECM remodeling and catabolism and have not been associated with periodontal disease to date." (PMID 34255809, 2021).
pterygium (1 paper, 2021). A wedge-shaped fibrovascular lesion arising from the bulbar conjunctiva and extending to the cornea. "In this study, multiple types of MMPs (MMP2, MMP3, MMP8, MMP9, MMP11, MMP16, and MMP28) were highly expressed in pterygium." (PMID 33790949, 2021).
rectal cancer (1 paper, 2024). A primary or metastatic malignant neoplasm that affects the rectum. "MMP11 mRNA expression was significantly higher in most cancers than in corresponding normal tissues, including colon and rectal cancers." (PMID 39239548, 2024).
skin cancer (1 paper, 2025). "MMP7, MMP11, and MMP14 play key roles in skin cancer progression." (PMID 40604111, 2025).
testicular germ cell tumor (1 paper, 2025). A germ cell tumor arising from the testis. "On the contrary, MMP11 was significantly lower in testicular germ cell tumors (TGCT)." (PMID 40607407, 2025).
urothelial carcinoma (1 paper, 2020). A malignant neoplasm derived from the transitional epithelium of the urinary tract (urinary bladder, ureter, urethra, or renal pelvis). "Matrix metalloproteinase 11 (MMP11) was suggested as a tumor marker of metastasis and predictor of poor survival in urothelial carcinomas." (PMID 31940762, 2020). "Recent study has suggested that the MMP11 may play a role as a marker of metastasis and predictor of poor survival in urothelial carcinomas." (PMID 31940762, 2020). "Previous study has suggested that the MMP11 may play a role as a predictor of poor survival and marker of metastasis in urothelial carcinomas." (PMID 31940762, 2020).
urothelial cell carcinoma (1 paper, 2020). "Conversely, patients with urothelial cell carcinoma who carried the MMP-11 rs131451 polymorphic “CC” genotype were associated with a lower risk of later tumor T status (T1-T4) when compared with those who carried the CT + TT genotype." (PMID 33228130, 2020).
Uterine leiomyoma (1 paper, 2016). The presence of a leiomyoma of the uterus. "In addition, RA induces overexpression of MMP11, which degrades IGF-binding proteins and may lead to cell proliferation, decreased apoptosis and accelerated ECM accumulation, thereby promoting the growth of uterine leiomyomas." (PMID 27070597, 2016).
tumor (244 papers, 1996 to 2026). "Matrix metalloproteinase‐11 (MMP11) has been implicated in tumor progression and extracellular matrix remodeling in various malignancies and has been shown to be progressively upregulated in IP transformation." (PMID 40843631, 2026). "Elevated MMP11 expression has been associated with increased tumor aggressiveness and poor prognosis in several malignancies, including breast, gastric, lung, pancreatic, and oral cancers." (PMID 40843631, 2026). "Meanwhile, we investigated MMP11 on PCa from the angle of immune-cell infiltration and regulation, tumor mutational burden (TMB), microsatellite instability (MSI), immunotherapeutic sensitivity, and drug sensitivity." (PMID 40607407, 2025). "To explore the association between MMP11+ mCAFs and the tumor immune microenvironment, we categorized samples from the TCGA‐BLCA dataset into two distinct molecular subtypes based on the signature gene expression profiles of MMP11+ mCAFs." (PMID 40552583, 2025). "In this study, we identified a prognostically unfavorable fibroblast subpopulation associated with tumor progression, characterized by high expression of MMP11, which we designated as MMP11+ mCAF." (PMID 40552583, 2025). "Western blot confirmed MMP11 upregulation in tumor-associated fibroblasts (CAFs) induced by conditioned medium compared to normal prostate fibroblasts." (PMID 40607407, 2025). "MMP11 serves as a key mediator of normal physiological tissue remodeling, and its upregulation has been previously associated with tumor initiation and malignant progression." (PMID 41009818, 2025). "MMP11 suppression inhibited PCa cell proliferation, migration, invasion, and epithelial-mesenchymal transition.MMP11 was predominantly expressed in fibroblasts and linked to the establishment of an immunosuppressive tumor microenvironment." (PMID 40607407, 2025). "This was confirmed with the multivariate linear regression model: MMP-11 immunohistochemical score was significantly associated with uPA (coefficient 8.8, p = 0.01) and tumor grade (coefficient 48.2, p = 0.007)." (PMID 38438841, 2024). "MMP-11 staining was primarily observed in cells having a typical fibroblastic morphology interspersing tumor epithelial cells known as cancer-associated fibroblasts (CAFs)." (PMID 38438841, 2024). "In 2016, MMP-11 overexpression was associated with aggressive tumor phenotype and unfavorable clinical outcomes in UTUC." (PMID 39063556, 2024). "MMP11-positive CAFs have been found enriched in the stroma of invasive ductal carcinoma, being associated with tumor progression and poor prognosis." (PMID 37168385, 2023). "The MMP-11 rs131451 “TC + CC” genotypic variants were correlated with greater tumor T status [OR (95% CI):1.254 (1.025–1.534); p = 0.028] and perineural invasion [OR (95% CI):1.773 (1.027–3.062); p = 0.040) in male CRC patients." (PMID 35885589, 2022). "The results demonstrated that the male CRC patients who carried the MMP-11 rs131451 “TC + CC” genotype were associated with greater tumor T status (p = 0.028) and perineural invasion (p = 0.040)." (PMID 35885589, 2022). "Considering MMP/TIMP expression, tumor budding showed a positive and significant association with MMP-11 (p = 0.029), MMP-14 (p = 0.024), and TIMP-1 (p = 0.021) expression by CAFs and MMP-14 expression by tumor cells (p = 0.034)." (PMID 33669393, 2021). "Expression data available in public repositories suggested that increased tissue expression of calpains 1 and 2 and MMP11 decrease overall patient survival and higher levels of meprin 1A can be associated with recurrence and tumor size." (PMID 33578082, 2021). "In silico cytometry showed that high MMP-11 expression was associated with low tumor antigenicity, reduced TILs, including CD8+ T cells, CD4+ memory T cells and memory B cells, and low activation of dendritic cells." (PMID 34038440, 2021).
tumor (continued). "Previous studies have reported that MMP-11 polymorphisms were associated with cancer risk and tumor development; however, the associations of the MMP-11 SNPs with cancer susceptibility varied in different cancers." (PMID 33228130, 2020). "Overexpression of MMP8 is significantly associated with higher clinical stage, overexpression of MMP11 is significantly associated with bigger tumor size, and low expression of MYB is significantly related to worse pathologic grade and metastasis." (PMID 32309437, 2020). "Previous studies have linked the MMP11 polymorphisms with cancer risk and tumor development, and it seemed that the impact of MMP11 SNPs to cancer susceptibility varied in different cancers." (PMID 31940762, 2020). "Altogether, these results show that the presence of MMP11 is associated with a metabolomic signature favoring tumor growth." (PMID 32825455, 2020). "In cancer, MMP11 expression is associated with poorer survival, and preclinical studies in mice showed that MMP11 accelerates tumor growth." (PMID 32825455, 2020). "MMP-11 (stromelysin-3) is preferentially expressed by peritumoral stromal cells and is associated with tumor progression and poor prognosis." (PMID 31086100, 2019). "MMP-7/9/12 (tumor-associated macrophages), MMP-9 (embryonic cells), MMP-11 (adipose cells) and a myriad of MMPs are known to interact with CAFs, while also causing a transition of mature stromal cells to tumor cells." (PMID 29881724, 2018). "MMP11 - also called stromelysin 3 – has already been associated with the invasion of tumour cells and is a marker of poor prognosis." (PMID 30236106, 2018). "In univariate analysis, CD147 expression (P = 0.001), MMP-11 expression (P = 0.011), differentiation (P < 0.001), lymphovascular invasion (P < 0.001), and tumor staging (P < 0.001) were associated with overall survival." (PMID 26507719, 2015). "In an initial approach, we analyzed 65 factors associated with tumor progression and inflammation, in a tumor population classified in good or bad prognosis, based on MMP-11 expression by intratumoral MICs." (PMID 23145063, 2012). "Such experimental evidence has provided a causative role for MMP-11 protein during tumor progression." (PMID 21513571, 2011). "Tumours with high expression of MMP-11 or -13, or cluster thereof, were significantly associated with higher probability of biochemical recurrence." (PMID 20160732, 2010). "Furthermore, previous research has demonstrated that androgen-induced miR-135a acts as a tumor suppressor in PCa cells by downregulating MMP11, and this mechanism was associated with developing androgen resistance." (PMID 40122809, 2025). "In univariate analysis, only tumor grade and uPA level were associated with MMP-11 expression." (PMID 38438841, 2024). "MMP11 expression is thought to be associated with clinical outcome in various tumours." (PMID 37664042, 2023). "Remodeling of the extracellular matrix of the surrounding adjacent tumor area may also be associated with adipocytes, as the release of collagen VI and matrix metalloproteinase 11 (MMP11) promotes cancer invasion." (PMID 37108109, 2023). "Interestingly, MMP-11 expression was associated with tumor progression and castration resistance in PCa." (PMID 37108185, 2023). "Indeed, in gain-of-function and loss-of-function experiments with mice, MMP11 has been shown to favour early tumour growth by boosting proliferation of cells and reducing their apoptosis by promoting metabolic flexibility that promotes tumour cell growth." (PMID 37391533, 2023). "Furthermore, serum MMP-11 levels in tumor tissue and serum have been reported to be useful diagnostic and prognostic biomarkers in advanced GC." (PMID 36139587, 2022). "However, the associations and influences of MMP-11 polymorphisms regarding CRC tumor progression and clinicopathologic characteristics remained uninvestigated." (PMID 35885589, 2022). "Reciprocally, MMP11 deficiency results in a mirror phenotype and delayed tumor growth." (PMID 32825455, 2020).